PLK1 (polo like kinase 1)
Diseases named in the same sentence as PLK1 in open-access papers (continued):
Sharing a sentence is not in itself a finding about the gene and the disease.
cancer (continued). "Therefore, all the analyses and experiments indicated that CR could induce the G2/M arrest by suppressing the PLK1/CDK1/Cyclin B axis, and ultimately inhibiting cancer cell growth." (PMID 37007025, 2023). "Moreover, multiple non-mitotic functions of Plk1 have been reported, such as metabolism, cancer cell EMT, mTOR regulation, and vascular homeostasis." (PMID 37640723, 2023). "The stress‐activated kinases c‐Jun N‐terminal kinase (JNK) and the mitogen‐activated protein kinase (MAPK) p38 play a key role in response to stress insults, and we therefore explored whether elevated ROS upon FGFR/PLK1 inhibition can activate JNK and p38 in KRAS‐mutant cancer cells." (PMID 34369083, 2021). "Our results suggested that Plk1 is also a marker of relapse/resistance in HNSCC and could represent a relevant therapeutic target for these cancers at the diagnosis as previously suggested 21, 22 but also at relapse on reference treatments by chemo/radiotherapy." (PMID 34646387, 2021). "Moreover, the pan-cancer analysis of the molecular function of Cdc20 indicated that BUB1, CCNA2, CCNB1, CDK1, MAD2L1, and PLK1 might play a critical role in interaction with Cdc20." (PMID 34527589, 2021). "Since ALKBH4 knockdown downregulated the expression of PLK1 and PLK4, ALKBH4 may function as a tumour promoter by accelerating cancer cell proliferation via upregulation of E2F1 signalling in early stage, and by promoting metastasis via upregulation of PLK signalling in late-stage NSCLC." (PMID 33883577, 2021). "In addition, the HPA data of CCND1, PLK1, and CD44 expression in tumor smaples exhibited high staining intensities, and all the IHC images were obtained from the HPA database to validate the expression of genes in the cancer types at the protein level." (PMID 34063946, 2021). "In this study, we demonstrated that, compared to cells with basal CCNA2 expression, cancer cells highly expressing CCNA2 are more addicted to PLK1 activity and show increased mitotic index values, leading to G2/M arrest and mitotic catastrophe, followed by apoptosis, in response to PLK1 inhibitors." (PMID 32486290, 2020). "As reported by others, highly expressed SMC4 may upregulate the expression of PLK1, leading to cancer progression and poor prognosis in non-TNBC." (PMID 33460400, 2020). "The PLK1 inhibitor BI2536 and its derivative BI6727 inhibit tumor growth in vitro and in the clinical setting, suggesting that a PLK1 inhibitor could be a monotherapy for cancer treatment." (PMID 31387297, 2019). "Thus, the beneficial effects in cancer patients of AZD1775 can be mechanistically interpreted as due to interference with the function of Wee1 rather than of Plk1." (PMID 31200459, 2019). "The fact that Plk1 may function as a tumor suppressor instead of an oncogene does not necessarily argue against the use of Plk1 inhibitors in cancer therapy." (PMID 30069007, 2018). "Normal, but not cancer, cells have previously been shown to survive PLK1 depletion." (PMID 28036269, 2017). "Furthermore, a robust ability of PLK1 to distinguish cancer from non-cancerous gastric tissues was observed via ROC (AUC: 0.86; 95% CI: 0.82–0.88, P<0.001)." (PMID 29190933, 2017). "If developed, Plk1 PBD inhibitors with superior specificity can be used not only as a single therapeutic agent but also as an agent easily amenable for combination therapy with other anti-cancer therapeutics." (PMID 28721210, 2017). "Therefore, we were encouraged to discover additional Plk1 PBD inhibitors, which could be used for anti-Plk1 cancer therapy." (PMID 27902479, 2017). "For instance, targeting PLK1 might be applied to a wide variety of cancers, regardless of their PLK1 expression levels, to prevent induction of EMT and tumor metastasis." (PMID 27003818, 2016). "Overall, our data support the hypothesis that PLK1 overexpression increases the vulnerability of cancer cells to PP2A inhibitors such as cantharidin or nor-cantharidin." (PMID 27557495, 2016).
cancer (continued). "Importantly, our data indicate that a treatment schedule in which a short Plk1 inhibition using BI2536 is performed before IR reduces the formation of BRCA1 and Rad51 foci, leading to impaired HR repair and to radiosensitization of cancer cells." (PMID 26745677, 2016). "Thus Chemistry_28272 and the other top compounds are novel Plk1-PBD inhibitors and could be used for the development of cancer therapeutics." (PMID 25036740, 2014). "The finding, that the combination of a Plk1 and a PKCβ inhibition reduces the cell proliferation of cancer but not of primary cells could be of great importance for the development of future anti-cancer therapy strategies." (PMID 24810255, 2014). "Since inactivation of DNA-PKcs, PLK1, PP6 or Chk2 leads to mitotic defects including misaligned chromosomes, lagging chromosomes and abnormal nuclear morphologies and cytokinesis, these findings have relevance to understanding the mechanism of aneuploidy in cancer cells." (PMID 24844881, 2014). "This leads to the hypothesis that Plk1 inhibition is specific and selective by targeting only cancer cells but not normal cells." (PMID 23948487, 2013). "Thus, we first compared PLK1 protein levels in the four cancer cell lines (HepG2, MG63, HeLa, and PC3) and a non-cancer cell line MRC5 (Human fetal lung fibroblast)." (PMID 23056340, 2012). "Moreover, inhibition of PLK1 by BI2536 could reduce gefitinib‐induced hepatotoxicity by restoring COX6A1 expression without impairing the anti‐cancer activity of gefitinib." (PMID 39994841, 2025). "Interestingly, tetraploid cancer cells showed sensitivity to some mitotic inhibitors, essentially inhibitors of Checkpoint kinase 1 (CHK1), Aurora B, Kinesin-5 (Eg5), Polo Like Kinase 1 (Plk1) and Monopolar spindle 1 (Mps1 also named threonine tyrosine kinase TTK)." (PMID 39940976, 2025). "The observed anti-cancer effects of PIAS2b-dsRNAi in both thyroid and non-thyroid anaplastic cells, including downregulation of PLK1, gTub, CDK1, and the presence of high-molecular weight PP2CA and PSMC5 bands, might be linked to this dysregulated proteasome activity." (PMID 38744818, 2024). "In addition, the heterogeneity of KRAS‐mutant cancers leads to limited efficacy of KRAS inhibitors (KRASi) as monotherapy; while their combination with other targeted agents, including SHP2, EGFR, PD‐L1, CDK4/6, PLK1, and IRE1α, significantly enhances anti‐tumor activity and overcomes resistance." (PMID 39254172, 2024). "Moreover, studies have shown that KIF20A interacts with other proteins involved in cell cycle regulation and cancer development, such as Aurora-A and PLK1, suggesting that KIF20A may play a crucial role in the regulation of cell division and cancer progression." (PMID 37310408, 2023). "Additionally, By interfering with PLK1’s proper cellular localisation, EGC, a distinct kind of catechin, has the capability to lead to cell-cycle arrest within G2/M as well as S phases, ultimately inducing death in a number of cancer cells, including HeLa cells." (PMID 38129839, 2023). "In addition, the expression of CDC25C (P = 0.000), pCDC25CSer216 (P = 0.000), CDK1 (P = 0.000), CHK1 (P = 0.000), CHK2 (P = 0.000), PLK1 (P = 0.000) and Aurora A (P = 0.008) between the primary carcinoma without metastasis and serious borderline cystadenoma were also statistically different." (PMID 32393310, 2020). "Therefore, these collective findings provide documentation that the significant reduction in overexpression of PLK-1 by small molecules, (si)RNA, antisense oligonucleotides, and phosphopeptides diminish the viability of cancer cells without affecting the viability of normal cells." (PMID 26557691, 2015). "However, the role of 15d-PGJ2 in modulating PLK1 has never been explored in cancer." (PMID 24566468, 2014).
cancer (continued). "Also, Liu and colleagues showed that normal cells but not cancer cells could survive severe Plk1 depletion." (PMID 23151088, 2012). "However, there are currently no clinical studies of PLK1 inhibitors in any pediatric cancers." (PMID 22390279, 2012). "Furthermore, we could not find any relationship between PLK1 expression and Ki-67 antigen expression in this carcinoma." (PMID 14735186, 2004). "However, despite the observations that PLK1 inhibition selectively reduces cell proliferation in cancer cells but not in normal cells, the clinical efficacy of PLK1 inhibitor is limited due to a lack of biomarkers that could be used to stratify patients who will respond to PLK1 inhibitor." (PMID 36980292, 2023). "Pharmacological and genetic suppression of FGFR1 and PLK1 synergizes to enhance anti‐proliferative effects and cell death in KRAS‐mutant lung and pancreatic but not colon nor KRAS wild‐type cancer cells." (PMID 34369083, 2021). "Although interesting clinical results suggest a possible role for TRAIL and PLK1 inhibition as monotherapy in cancer therapy, combined use of TRAIL receptor agonists and PLK1 inhibitors has not yet been investigated." (PMID 29983892, 2018). "Intriguingly, inhibition of Plk1 PBD function alone is sufficient for effectively imposing mitotic arrest and apoptotic cell death in cancer cells but not in normal cells." (PMID 28721210, 2017). "These experiments imply that the regulation of Plk1 and RSK1 in stem cells is different from that in non-stem cells such as cancer cells." (PMID 28430578, 2017). "First, we determined the levels of Plk1 mRNA after treatment with SAHA alone and in combination with SBE13 in HeLa (cancer cells), hTERT-RPE1 (non-transformed immortalized) and NIH-3T3 cells (mouse fibroblasts)." (PMID 26317649, 2015). "Such co-regulation in cancer samples has not previously been investigated; as studies have been limited to studying either FOXM1 or PLK1 expression in these tumours." (PMID 26576650, 2015). "Unlike other mitotic factors like Aurora A, Aurora B, and PLK1, that are normally essential, MELK presents a unique mitotic kinase that is only required by a subset of cancer cells, and is therefore an excellent therapeutic target." (PMID 24844244, 2014). "Recently, it has been shown that depletion of Plk1 suppresses the viability of MCF10A, a non-transformed mammary epithelial cell line, even more strongly than that of cancer cell line MDA-MB-468 in monolayer cell culture system." (PMID 23948487, 2013). "Although this correlation is not absolute, it suggests that targeting PLK1 and AURKA could be effective in cancers characterized by high MYC family gene expression." (PMID 39085197, 2024). "And while we observe some anti-cancer effects of PLK1is as single agents in MYC-non-amplified background, it is less significant compared to MYC-amplified cells, possibly due to moderate expression of and dependence on of MYC and/or PLK1." (PMID 37183219, 2023). "Unlike the well-established oncogenic function of PLK1, the role of PLK2 in human cancers remains unclear." (PMID 35156101, 2021). "Unlike PLK1, PLK2 functions as a tumor suppressor in some cancer types." (PMID 33176854, 2020).
cancer (continued). "However, the situation was different in the cancer cells: inhibition of Plk1 activated RSK1 via its upstream kinase MEK/ERK, and Plk1 activity was not affected by RSK1 suppression." (PMID 28430578, 2017). "Since Plk1-dependent signaling pathways and biochemical steps are predictably rewired in Plk1-addicted cancers, it would be feasible to tailor PBD inhibitors in such a way that they would interfere with PBD-dependent interactions enriched in cancer cells, but not normal cells." (PMID 26500787, 2015). "In all three cell lines, regardless whether they are cancer cells (HeLa), non-transformed immortalized cells (hTERT-RPE1) or completely normal fibroblasts (NIH-3T3) the Plk1 protein was significantly reduced by SAHA treatment." (PMID 26317649, 2015). "In the current study we analyzed for the first time the effects of PKCβ inhibition using Enzastaurin in combination with Plk1 inhibition using SBE13 on cell cycle regulation and induction of apoptosis in different cancer cell lines and in immortalized, but not transformed hTERT-RPE1 cells." (PMID 24810255, 2014). "With above results, it is suspected that PLK1, MCM complex, SKP2 and some of their interacting genes may play important roles to promote cell cycle related processes in cancer but not normal cells." (PMID 22838965, 2012). "Therefore, we analyzed in the present study whether and what type of crosstalk exists between PLK1, MTORC1, and autophagy in nonmitotic cancer cells." (PMID 28102733, 2017). "Therefore, unlike inhibiting Plk1 KD, antagonizing the PBD function may allow one to uniquely impose an additional layer of selectivity in killing cancer cells, but not normal cells." (PMID 26500787, 2015).
tumor (751 papers, 2004 to 2026). "Elevated PLK1 expression was strongly associated with advanced clinicopathological stages (tumor/node/metastasis (T/N/M)) and poorer overall survival." (PMID 41556056, 2026). "Targeting PLK1 markedly inhibits cell proliferation, causes cell cycle G2 phase arrest and DNA damage, induces apoptosis, and reduces tumor growth in preclinical models of EOC." (PMID 41458961, 2025). "Our results showed that the mRNA expression level of PLK1, the molecular target of Volasertib, was elevated in tumor tissues, particularly in high risk HCC patients." (PMID 40474968, 2025). "BI6727 selectively inhibits PLK1, inducing G2/M phase arrest and apoptosis in various tumor cells while causing reversible G1 and G2 phase arrest without apoptosis in normal cells." (PMID 40093330, 2025). "The study reported that by mediating YTHDF1’s overexpression, ELK1 is implicated in the expression of polo-like kinase 1 (PLK1), which promotes cell cycle progression and contributed to tumor growth and chemoresistance." (PMID 40862737, 2025). "High expression of PLK1 plays a critical role in driving tumorigenesis and is closely associated with tumor initiation, progression, and poor prognosis." (PMID 40809688, 2025). "On the other hand, PLK1 has been shown to promote the polarization of tumor-associated macrophages (TAMs) from the M1 to the M2 phenotype." (PMID 40612941, 2025). "PLK1 (Polo-like kinase 1) is overexpressed in PCa and is associated with higher tumor grades, suggesting its involvement in tumorigenesis and disease progression." (PMID 41402347, 2025). "In sum, these results supported the notion that high PLK1 was associated with increased tumor-promoting M2-like macrophages in LUAD." (PMID 38885192, 2024). "To validate the anti‐tumour effects of PLK1 suppression in vivo, we utilized a subcutaneous xenograft nude mouse model with intratumoral delivery of lentiviral vectors encoding PLK1‐targeting sgRNAs." (PMID 38780513, 2024). "PLK1‐mutated CRCs exhibited higher tumour mutation burden (TMB) than PLK1‐mutated NSCLCs, which were the majority of the LC cohort." (PMID 38887977, 2024). "A single intracerebral injection of CRISPR-LNPs against PLK1 in aggressive orthotopic GB caused tumor cell apoptosis, inhibited tumor growth by 50%, and improved survival by 30% but showed diverse adverse effects." (PMID 38473776, 2024). "In patients treated with neoadjuvant chemoradiotherapy (preoperative therapy), high expression of PLK-1 was linked to poorer tumor regression and a greater likelihood of local disease recurrence." (PMID 39857637, 2024). "Polo-like kinase 1 (PLK1) is a key regulator of mitosis and cytoskeletal dynamics that is overexpressed in a range of tumours and is associated with tumour progression, metastasis, and vascular invasion." (PMID 37648284, 2023). "The immunological risk model we developed on the basis of PLK1 is capable of effectively predicting patient prognosis, tumor growth, the extent of immunotherapy and chemotherapy response, and identifying gene alterations." (PMID 36951624, 2023). "We further developed a CAST platform equipped with a PLK1-specific ASO to logically regulate PLK1 gene expression which is highly associated with tumor cell proliferation, to verify CAST effectiveness." (PMID 37580346, 2023). "Studies have shown that increased G2/M population and apoptosis induction in tumor cells are associated with response to Aurora kinase or PLK1 inhibition, which is in accordance with our results." (PMID 37259298, 2023). "In a general, high PLK1 expression tends to be associated with more aggressive tumor traits and a higher mitotic score." (PMID 38234395, 2023).